IL10 (interleukin 10)
Diseases named in the same sentence as IL10 in open-access papers (continued):
Sharing a sentence is not in itself a finding about the gene and the disease.
sarcoidosis (continued). "Active chronic sarcoidosis patients had significantly less circulating memory B cells (p<0.01), more transitional (p<0.01) and increased numbers of IL-10-producing regulatory B cells (p<0.05) compared with healthy donors and patients with inactive sarcoidosis." (PMID 22927996, 2012). "Levels of IL-1β and IL-10 were significantly elevated in both diseases compared to healthy BALs, whereas levels of IL-2 were significantly increased in sarcoidosis only." (PMID 22815689, 2012). "Inactive sarcoidosis patients (n = 11) had similar percentages and absolute numbers of IL-10-producing B cells as healthy controls (n = 15)." (PMID 22927996, 2012). "Decreased memory and increased transitional and increased IL-10-producing regulatory blood B cells were characteristic of sarcoidosis patients in the active disease phase." (PMID 22927996, 2012). "Less IL-10 produced by monocytes resulted in impaired suppression of T-cell proliferation, possibly contributing to the exaggerated T-cell alveolitis observed in sarcoidosis." (PMID 33446605, 2021). "As invariant natural killer T (iNKT) cells are known to both interact with monocytes and be reduced in sarcoidosis patients, we then asked whether iNKT‐specific defects might be responsible for this reduced IL‐10 production." (PMID 24723379, 2014). "We found that the higher the numbers of circulating iNKT cells, the greater the capacity for IL‐10 production by monocytes when stimulated with LPS (r2 = 0.6; p = 0.0004) when all the data (i.e. sarcoidosis and controls, due to poor range in iNKT‐cell numbers in sarcoidosis patients)." (PMID 24723379, 2014). "Of particular interest in sarcoidosis is that IL-10 can inhibit an experimental granulomatous inflammation and that corticosteroids, which are usually used to treat the disease, have the capacity to enhance IL-10 production." (PMID 25180094, 2014). "Although the focus of the study is on IL‐10 producing monocytes, the reduction of iNKT cells in sarcoidosis patients may be worth a mention." (PMID 24723379, 2014). "To explore if there were a relationship between the previously observed reduction in iNKT‐cell numbers and the defect in IL‐10 production by monocytes in sarcoidosis, we first examined the number of circulating iNKT cells with IL‐10 producing capacity of monocytes in sarcoidosis and normal controls." (PMID 24723379, 2014). "We suggest that reduced iNKT‐cell numbers in sarcoidosis may lead to impaired monocytic IL‐10 production and unchecked T‐cell expansion in sarcoidosis." (PMID 24723379, 2014). "Defective IL‐10 production and T‐cell suppression by sarcoidosis monocytes could be restored following their coculture with iNKT cells, in a CD1d‐ and cell contact‐dependent process." (PMID 24723379, 2014). "In summary, the IL10 polymorphisms do not appear to be significantly relevant to Japanese sarcoidosis patients." (PMID 22393278, 2012). "Thus, the level of IL-10-producing B cells was evaluated in active and inactive sarcoidosis patients and healthy controls." (PMID 22927996, 2012). "Here we report a lack of association between IL10 variants and Japanese sarcoidosis patients, suggesting that the possibility of attributing the pathogenesis of sarcoidosis to IL10 genetic variations is low." (PMID 22393278, 2012). "Our results suggest that IL10 polymorphisms are not significantly related to the pathogenesis of sarcoidosis in the Japanese population." (PMID 22393278, 2012). "Similarly, comparing the protein concentration of IL-10 in the bronchoalveolar lavage (BAL) of patients with different types of ILDs the highest level of IL-10 was demonstrated in patients with IPF compared with sarcoidosis or hypersensitivity pneumonitis." (PMID 26199463, 2015). "As with the previous report, we could not find any association between IL10 gene polymorphisms and sarcoidosis." (PMID 22393278, 2012). "In addition, increased serum levels of IL-10 in sarcoidosis patients have been reported." (PMID 22393278, 2012).
sarcoidosis (continued). "Here, we found that there is a significant heterogeneity among sarcoidosis patients with respect to serum cytokine profile, including IL-18, IFN-γ, IL-10 and MIF." (PMID 36207373, 2022). "Further experimental studies need to elucidate the MIF role in IL-10 and IFN-γ as well as B cell function in sarcoidosis." (PMID 36207373, 2022). "In an independent subgroup of CVID patients, sarcoidosis patients as well as healthy donors we performed an analysis by MultiPlex Bead Arrays of BAL fluids for CXCL10, IL-4, IL-10, IL-12, and IL-17." (PMID 33613543, 2020). "Unselected BAL cells from sarcoidosis subjects co-cultured with MSCs showed a reduction in TNF-α (pro-inflammatory M1) and an increase in IL-10 (anti-inflammatory M2) in 9 of 11 samples studied." (PMID 31963936, 2020). "In the non-infectious group, there seemed to be a difference in the expression levels of other cytokines (MCP-1, IFN-γ, and IL-10) between the eyes with IOL and those with sarcoidosis." (PMID 32066796, 2020). "In a separate assay, one of the two sarcoidosis subjects whose BAL was analyzed by flow cytometry showed a similar change—a small increase in TNF-α and a larger increase in IL-10." (PMID 31963936, 2020). "Although acute sarcoidosis is generally characterized by a proinflammatory TH1/M1 cell response, increased IL-10 messenger RNA (mRNA) levels have been detected in newly diagnosed patients with active sarcoidosis." (PMID 33036432, 2020). "DEX treatment decreased expression of numerous cytokine and chemokine genes in sarcoidosis monocytes, while increasing the expression of CXCL10 and IL-10." (PMID 32477331, 2020). "The main results obtained from this study show that patients with sarcoidosis had a significantly higher secretion of inflammatory cytokines TNF-α, IL-6, IL-10 and IL-12 after in vitro co-stimulation of PBMCs with FCWAs and LPS." (PMID 27688795, 2016). "Our results showed that patients with sarcoidosis, compared to healthy subjects, had a significantly higher secretion of inflammatory cytokines TNF-α, IL-6, IL-10 and IL-12, after co-stimulation of PBMCs with FCWAs and LPS." (PMID 27688795, 2016). "In in vitro studies on the reactivity of peripheral blood mononuclear cells (PBMC), particulate β-glucan was found to induce the secretion of TNFα, IL-6, IL-10, and IL-12 from PBMC with a higher secretion from PBMC taken from patients with sarcoidosis." (PMID 25180094, 2014). "However, in the present study, IL-10 was selectively increased in IOL whereas bFGF, IFN-γ, IL-6, and IL-8 were also elevated in sarcoidosis, ARN, and BE." (PMID 32066796, 2020). "Patients with sarcoidosis had a significantly higher secretion of inflammatory cytokines tumour necrosis factor-alpha (TNF-α), interleukin-6 (IL-6), IL-10 and IL-12 (1.7-fold, 2.0-fold, 2.2-fold, and 2.8-fold, respectively; all p < 0.05) after in vitro co-stimulation of PBMCs with FCWAs and LPS." (PMID 27688795, 2016). "In the whole blood assay used in the present study, we did not demonstrate that the IL-10 regulatory axis was dysfunctional in sarcoidosis, and the expression profiles of regulatory SIRP-α/CD47 were also similar between sarcoidosis and healthy subjects." (PMID 27929051, 2016). "Our study shows that monocytes from patients with sarcoidosis do not produce IL‐10 to the same level as healthy controls and are functionally less capable of suppressing T‐cell proliferation." (PMID 24723379, 2014). "First we studied the relative gene expression of the typical M1 markers, IL-12p35, IL-23p19, CCR7, and M2 markers, IL-10 and CCR2, in total BAL cells of sarcoidosis patients and healthy subjects after culturing in medium for four or 24 h, or after 24 h of LPS stimulation." (PMID 20813038, 2010).
sarcoidosis (continued). "The IL-10 level in IOL (780.3 ± 684.3 pg/ml, 100% detection) was respectively about 1400-fold, 620-fold, 4.0-fold, and 7.8-fold higher than that in ERM (0.56 ± 0.60 pg/ml, 47%), sarcoidosis (1.26 ± 1.30 pg/ml, 53%), ARN (194.9 ± 135.2 pg/ml, 92%), and BE (100.2 ± 197.7 pg/ml, 94%)." (PMID 32066796, 2020). "IFNγ and IL-10 were not significantly different between sarcoidosis patients and healthy controls." (PMID 27929051, 2016). "Our data supports this, and could also explain the ‘‘immunologically exhausted’’ nature of FoxP3 Treg cells observed in sarcoidosis 16 since these cells are functioning without the contribution from IL‐10 producing monocytes." (PMID 24723379, 2014). "ELISA measurements of these co-culture supernatants showed that BAL cells from sarcoidosis subjects significantly decreased their TNF-α production (p = 0.029) and increased their IL-10 production (p = 0.011), unlike cells from control subjects." (PMID 31963936, 2020). "In our cytokine ELISA assays of co-culture medium, two sarcoidosis subjects did not follow the trend of decrease in TNF-α and increase in IL-10 (like all the other patients)." (PMID 31963936, 2020). "In another study, it was reported that the repressor activity was impaired only in BALF Tregs and not in the peripheral blood Tregs of sarcoidosis patients, taking telomere length and the ability to produce transforming growth factor beta (TGF-β) and IL-10 into account." (PMID 37520566, 2023).
acute coronary syndrome (33 papers, 2007 to 2025). Signs and symptoms related to acute ischemia of the myocardium secondary to coronary artery disease. "Elevated serum IL‐10 levels have been linked to a more favorable prognosis in patients with acute coronary syndrome." (PMID 39801756, 2025). "Compared to stable CAD and healthy subjects, acute coronary syndromes are associated with long-term increases in serum concentrations of anti- and pro-inflammatory cytokines, such as IL-2, IL-10, and TNF." (PMID 38541966, 2024). "The decreased levels of the anti-inflammatory cytokine IL-10 in acute coronary syndrome were found to be associated with the increased cardiovascular risk and clinical instability." (PMID 29742255, 2018). "Decreased IL-10 levels are found at the onset of acute coronary syndrome and increased concentrations have been associated with improved prognosis." (PMID 25923658, 2015). "Similarly, reduced IL-10 serum levels were associated with a more unfavorable prognosis in patients with acute coronary syndromes." (PMID 34336007, 2021). "Also, it is known that increased serum IL-10 levels are associated with a positive prognosis in acute coronary syndrome patients." (PMID 29742255, 2018). "Moreover, in patients with acute coronary syndromes it has been demonstrated that elevated serum IL-10 levels are associated with a significantly improved outcome." (PMID 24040186, 2013). "Moreover, in a large cohort of patients affected by acute coronary syndromes, elevated IL10 serum levels have been associated with a more favourable prognosis." (PMID 20467464, 2010). "Notably, IL6/IL10 imbalance has been previously associated with incidence and severity of CV events in patients with acute coronary syndrome while it has been demonstrated that the overexpression of IL10 exerts an inhibitory effect on the atherosclerotic plaque formation." (PMID 35178353, 2022). "Previous research on acute coronary syndrome concluded that the IL-18/IL-10 ratio had a positive predictive value for disease effects and adverse hospital outcomes." (PMID 39080003, 2024). "Interleukin-10 (IL-10) is an immunomodulatory cytokine that plays a pivotal role in the pathogenesis of acute coronary syndromes (ACS)." (PMID 38851847, 2024). "In a genome-wide association study that investigated patients with the acute coronary syndrome, genetic variants at the ABO blood group locus were associated with interleukin-10 levels." (PMID 36836590, 2023). "In the CAPTURE trial, elevated serum IL-10 levels correlated with significant improvement in prognosis in those with acute coronary syndrome (ACS)." (PMID 34660716, 2021). "On the other hand, an elevated baseline plasma level of IL-10 has been reported as a strong and independent predictor of long-term adverse cardiovascular outcome in patients with acute coronary syndrome." (PMID 23185530, 2012). "Some clinical studies have shown that patients with acute coronary syndrome have reduced IL-10 levels compared to stable patients, raising the possibility that low levels of IL-10 may be related to atherosclerotic plaque instability." (PMID 27026087, 2016). "Nicorandil suppresses the inflammatory cytokines IL-1β, IL-1, IL-6, IL-10, IL-18, IL-19 and TNF-α in acute coronary syndrome patients." (PMID 34595611, 2023). "Anti-inflammation strategy may be good for myocardial prognosis, but some anti-inflammatory cytokines such as IL-10 and TGF-β reduced in acute coronary syndrome (ACS) patients, reflecting the imbalance in systemic cytokine response following an ACS." (PMID 26819499, 2015). "The predictive value of IL10 was independent of myocardial necrosis but significantly interacted with CRP concentration, suggesting the importance of the balance between pro-inflammatory and anti-inflammatory cytokines as a major determinant of patient’s outcome in acute coronary syndromes." (PMID 23941335, 2013).
cognitive decline (33 papers, 2013 to 2025). "Third, well‐designed cohort studies are needed to further clarify the causal relationship between IL‐10 (or miR‐let‐7c‐5p), and diabetic cognition decline." (PMID 37532673, 2023). "Nevertheless, recent research has demonstrated that increased IL-10 production delays the transition from MCI to dementia, whereas decreasing IL-10 production over time is associated with worse cognitive decline in MCI patients." (PMID 36613538, 2022). "Of note was the association of IL-10 with both brain atrophy and rate of cognitive decline, adding further confidence to the finding of its association with AD-related endophenotypes." (PMID 26635716, 2015). "Furthermore, we found a complex relationship between CSF IL-10 levels, AD, and cognition, but associated lower CSF IL-10 levels to faster cognitive decline in MCI." (PMID 30253800, 2018). "Furthermore, it has been suggested that the IL-10 gene polymorphisms process, which favours the development of AD, reinforces the link between inflammation and cognitive decline in elderly people." (PMID 29854069, 2018). "Studies in mice have demonstrated that a reduction in gut dysbiosis due to the regulation of inflammatory and anti-inflammatory cytokine expression, may delay cognitive deficits, whereas a decrease in IL-10 production over time is associated with worse cognitive decline." (PMID 36613538, 2022). "After a two-year follow-up, AD patients with the highest BB-DNA tertile had a worse cognitive decline, while higher BB-DNA levels were associated with higher TNF-α and lower IL-10 in MCI." (PMID 36613538, 2022). "These IL-10(-/-) mice also produce more pro-inflammatory cytokines IL-1β, IL-6 and TNF-α in the plasma, suggesting IL-10 inhibits cognitive decline via its propensity to mitigate inflammation." (PMID 35308288, 2022). "P. gingivalis IgG concentration, TNF-α, and IL-10 correlated with the progress of cognitive decline." (PMID 32054121, 2020). "We observed five proteins that were associated with brain atrophy measures (IL-1ra, IL-6, IL-10, TNF-α, and IL-13) and six proteins that were associated with rate of cognitive decline in AD (IL-4, IL-10, G-CSF, IL-2, IFN-γ, and PDGF)." (PMID 26635716, 2015). "Specifically, we found a significant increase in the levels of IL-4 (p = 0.024), IL-10 (p = 0.040) and G-CSF (p = 0.046) in AD patients with a fast cognitive decline compared to slow cognitive decline in ADAS-cog over one year." (PMID 23762274, 2013). "For example, elevated serum CRP-levels were associated with cognitive decline in elderly women, and serum levels of CRP, Interleukin-6 and Interleukin-10 were negatively associated with a composite score of executive function and processing speed, but not with verbal episodic memory." (PMID 37467176, 2023). "Anti-inflammatory cytokines such as Interleukin-10 (Il-10) reduce inflammation during AD pathogenesis with increased levels in the central and peripheral nervous systems indicating disease severity with rapid cognitive decline." (PMID 38322496, 2023). "The presence of systemic infections and increased blood (plasma or serum) concentrations of cytokines including interleukin 1β (IL1β), interleukin 10 (IL10), interleukin 6 (IL6), and tumour necrosis factor α (TNFα) have been associated with sAD and predict cognitive decline." (PMID 30902060, 2019). "However, the results suggest that IL-10 may contribute to VX-765’s beneficial effect against cognitive decline in J20 mice." (PMID 36220815, 2022). "-MaR1 improved cognitive decline by reducing pro-inflammatory cytokines (TNF-α, IL-6, MCP-1) and increasing anti-inflammatory cytokines (IL-2, IL-10) levels." (PMID 39452854, 2024). "Inflammatory cytokines, including IL-6, IL-10, CRP, MCP-1, ICAM-1, and TNF-α, play an important role in the development of poststroke cognitive decline." (PMID 35111122, 2021).
cognitive decline (continued). "In addition, cytokines including IL-10, IL-6, and TNF regulate synaptic pruning, elimination, and plasticity; their imbalance may therefore cause excessive synapse loss or impaired circuit refinement, ultimately leading to cognitive decline or visual dysfunction." (PMID 41226665, 2025). "MCR participants had the highest TNF-α level (9.5 ± 2.6 pg./mL) compared with slow gait (8.5 ± 2.8 pg./mL), subjective cognitive decline (7.1 ± 1.4 pg./mL) and healthy (7.0 ± 1.7 pg./mL) groups and, conversely, the lowest progranulin/TNF-α and IL-10/TNF-α ratio." (PMID 37371414, 2023). "Differential expression of inflammation-related genes was observed in healthy children with DS; IL-10 levels were higher in DS individuals with AD and also in those with DS without a clinically relevant cognitive decline." (PMID 30186038, 2018). "However, evidence that multiple serum and CSF proinflammatory cytokines and chemokines, including IL-2, IL-1β, IL-6, IL-10 and IFN-γ, decline over time and may be undetectable in AD suggests that related topic study outcomes can vary with disease stage and cognitive decline." (PMID 37760836, 2023).